IL10 (interleukin 10)
Diseases named in the same sentence as IL10 in open-access papers (continued):
Sharing a sentence is not in itself a finding about the gene and the disease.
tumor (continued). "In response to tumour-derived IL10 and VEGF, for instance, excessive Stat3 activity in myeloid cells inhibits maturation and activation within the DC lineage, favours polarization and activation of tumour associated macrophages (TAM), and reduces cytotoxic activity of neutrophils and NK cells." (PMID 20478049, 2010). "In the present study we tested the hypothesis that IL-10 is part of the mechanism by which tumor infiltrating macrophages inhibit anti-tumor T cell activity." (PMID 20525400, 2010). "Although several cytokines are expressed by tumor macrophages and may have a potential role in tumor growth, this work focuses on IL-10, due to its role as a regulator of T cell activity." (PMID 20525400, 2010). "Hence, evidence is accumulating that CLR recognition of tumor glycans leads to the expression of the potent immunoregulatory cytokine IL-10." (PMID 21331365, 2010). "Furthermore, we observed that IL-10 is necessary for the expansion of B cells in the lymph nodes of tumor bearing mice." (PMID 20525400, 2010). "Indeed, suppression in the tumor microenvironment is mediated by a unique subset of CD4+CD25highFoxp3+ Tregs that produce IL-10 and TGF-β, exerting a more suppressive effect on proliferation." (PMID 21437225, 2010). "In contrast, tumors may induce immune dysfunction, e.g. by the release of immunosuppressive substances such as interleukin-10, or by an active counter-attack that induces apoptosis in the tumor-infiltrating leukocytes." (PMID 20626867, 2010). "Tumor-associated Tregs express the IL-23 receptor, which activates STAT-3 in this cell type, leading to upregulation of the Treg-specific transcription factor FoxP3 and the immunosuppressive cytokine IL-10." (PMID 19900287, 2009). "In tumor cells, STAT3 activation has been linked to both inhibition of pro-inflammatory cytokine secretion and induction of anti-inflammatory cytokine secretion, such as IL-10 and VEGF." (PMID 19718269, 2009). "Pretreatment of monocytes with JSI-124, resulted in a significant reduction in STAT3 activity (measured by both STAT3 transcription factor assay or phospho-STAT3 intracellular immunostaining) and in IL-10 production by the monocytes in tumor cell:monocyte co-cultures." (PMID 19718269, 2009). "BTM mice showed a significant increase in IL-10 production throughout tumor progression." (PMID 19534779, 2009). "Inhibition of HO-1 reversed the inhibitory effect of IL-10 on TNFα production Therefore, inhibition of HO-1 in tumor tissues may increase TNFα production, hence increasing the inflammatory response of the host." (PMID 19508729, 2009). "Moreover, it has recently been reported that DCs are capable of inducing conversion of naive CD4+ T cells to adaptive CD4+ CD25+ Foxp3+ Treg in the presence of TGF-β or IL-10 derived from tumor cells." (PMID 20182533, 2009). "Furthermore, tumor multiplicity was 5-fold higher in Il10−/− mice with an average of 1- compared to only 0.2 tumors in WT mice (p = 0.034)." (PMID 19551144, 2009). "Furthermore, IL10 expression has been correlated with tumor progression being of prognostic value in distinct entities." (PMID 19750229, 2009). "In addition, tumor cells secrete several anti-inflammatory cytokines such as IL-10 and TGF, which can suppress the functions of DCs." (PMID 18533025, 2008). "If circulating Treg and tumor-infiltrated Treg have enhanced function as a result of these elevated concentrations of IL-10 and TGF-ß, further aggressive progression of asbestos-induced cancer cells may have occurred." (PMID 21157517, 2008). "Thus, the source of the elevated TGF-ß and IL-10 concentrations in MM patients is not only tumor cells, but also immunocompetent cells." (PMID 21157517, 2008). "Thus, IL-10 would maintain a chronic inflammatory state within the tumor microenvironment and it would also inhibit recruitment and activation of adaptative immune system." (PMID 18221542, 2008).
tumor (continued). "It is tempting to speculate that circulating lymphocytes are entrapped by CD54-expressing tumour neovessels and become exposed to inhibitory cytokines (e.g. IL-10) and other bioactive substances originating in the tumour site." (PMID 17325703, 2007). "IL-10, the most potent Th2 polarizing cytokine, suppresses the tumoricidal activity of macrophages, blocks presentation of tumor antigens to professional APCs, and inhibits tumor-specific cytotoxic T cells." (PMID 16478542, 2006). "Similarly to activated T cells, various tumor cells secrete immune response-polarizing cytokines (IL-10, IL-6, IL-8, IL-13, TGF-β) serving as autocrine and/or paracrine growth factors for the cancer." (PMID 16478542, 2006). "Several tumour-derived products present in sera and tumour extracts from cancer patients, including transforming growth factor β (tgfβ), prostaglandin E2, interleukin-10, and vascular endothelial growth factor 1–4, have been identified and employ a variety of mechanisms to promote tumour growth." (PMID 17576455, 2006). "IL-10 expression thought to be a mechanism by which EBV-infected NPC cells counter the local immune defense by reducing the number of cytotoxic T-cells in the tumour microenvironment." (PMID 16995954, 2006). "More recently, interleukin-10 has been recognised to be an important immunosuppressive cytokine for the Th1 anti-tumour response and may be important in determining tumour growth and metastases." (PMID 17003778, 2006). "It is known that tumor cells secrete immunosuppressive cytokines such as IL-10 and TGF-β, and the cytokines may induce CD4+CD25- lymphocytes to convert to CD4+CD25+ TR cells." (PMID 15679891, 2005). "Thus, the IL-10/IL-10R axis is of import in controlling tumour metastasis and the development of therapeutic approaches which target this pathway is ongoing in our lab." (PMID 12771930, 2003). "Using immunohistochemistry, IL-10 was detectable in 10 of 21 tumour samples tested." (PMID 10408703, 1999). "The Tc response is strictly depending on tumor-derived IL-10." (PMID 9814607, 1998). "Furthermore, IGF2BP2 deficiency impaired tumor-associated macrophage (TAM)-like polarization in vitro, as evidenced by decreased expression of TAM markers, such as Mrc1, Mmp2, and Il10." (PMID 41943844, 2026). "For example, regulatory T cells (Tregs) can suppress the tumor-killing activity of CD8+ T cells, while M2-type tumor-associated macrophages promote tumor immune evasion by secreting immunosuppressive factors (IL-10, TGF-β) and facilitating angiogenesis and matrix remodeling." (PMID 40881169, 2025). "Although prior studies suggest that Clostridium butyricum could modulate the gut microbiota and promote anti-inflammatory immune responses such as inducing IL-10–producing macrophages and enhancing tumor immunity, we were unable to measure these mechanisms in this study." (PMID 41425719, 2025). "The results showed that compared to cGAMP, XA5508 could significantly increase the expression levels of immune factors IFN-β, IFN-γ, IL-2, IL-6, and TNFα in the mice, and significantly reduce the expression of the immunosuppressive tumor-promoting factor IL-10." (PMID 40943568, 2025). "Depending on the context, IL-10 may exert both tumor-promoting and -suppressing effects." (PMID 41155334, 2025). "Besides, M2-type tumor-associated macrophages (TAMs) secrete inhibitory cytokines under tumor hypoxic conditions, such as transforming growth factor-β and interleukin-10 (IL-10), which together constitute an inhibitory immune TME to block the entry of killer immune cells." (PMID 41340912, 2025). "On the other hand, blocking IL-10 or its receptor could potentially enhance anti-tumor immunity." (PMID 41007766, 2025).
tumor (continued). "However, tumor-derived cytokines and growth factors, notably IL-10, VEGF, and TGF-β, can skew DC differentiation toward a tolerogenic phenotype characterized by reduced expression of costimulatory molecules, impaired antigen presentation, and increased secretion of immunosuppressive cytokines." (PMID 40936894, 2025). "The immunosuppressive tumor microenvironment (TME) further compounds resistance as HPV-associated cancers often harbor regulatory T cells (Tregs), myeloid-derived suppressor cells (MDSCs), and immunosuppressive cytokines such as Transforming Growth Factor-beta (TGF-β) and Interleukin-10 (IL-10)." (PMID 40282436, 2025). "Moreover, the interaction between B cells and TNBC tumor cells, leading to an upregulation of the inflammatory cytokines IL-4 and IL-10 that drive the chronic inflammatory response of the tumor, may impede the antibody-mediated immune response." (PMID 40079015, 2025). "IL‐10 is a common anti‐inflammatory cytokine, but elevated levels of IL‐10 can suppress patient immune responses, thus promoting the formation of the tumor microenvironment before metastasis and increasing tumor cell immune evasion, ultimately facilitating tumor metastasis." (PMID 40808216, 2025). "Tregs are a specialized subset of CD4+ T cells that accumulate in large numbers within the tumor and peripheral blood, where they suppress cytotoxic T lymphocytes and natural killer (NK) cells, decrease antigen-presenting cell function, and secrete inhibitory cytokines, such as IL-10 and TGF-β." (PMID 41374979, 2025). "Thus, further investigation is needed to elucidate the mechanisms by which IL-10 may contribute to either tumor suppression or progression." (PMID 41267807, 2025). "Through the JAK-STAT pathway (specifically STAT3), IL-10 signaling inhibits dendritic cell maturation, reduces pro-inflammatory cytokine production by macrophages and other cells, and attenuates T-cell activation, thereby effectively suppressing anti-tumor immunity." (PMID 41006647, 2025). "However, changes in the levels of IL‐10 in response to tumour growth were evident." (PMID 40172096, 2025). "Additionally, modulating DC-SIGN signaling and IL-10 production may help reshape the tumor microenvironment, potentially inhibiting tumor progression and metastasis." (PMID 40076949, 2025). "Furthermore, treatment of CLL cells with ibrutinib and venetoclax, after coculturing the tumor cells with TME agonists such as interleukin-10 (IL-10), CD40L, and CpG-ODNs (TLR-9 specific agonists), led to the activation of the NF-κB signaling pathway (especially alternative NF-κB)." (PMID 40555733, 2025). "This dual behavior reflects an insufficient anti-inflammatory counterbalance in the tumor-driven pro-inflammatory environment, where compensatory increases in IL-4 and IL-10 may become saturated, thereby limiting their regulatory capacity and contributing to cancer-related cognitive dysfunction." (PMID 41155372, 2025). "On the contrary, M2 TAMs are characterized by an anti-inflammatory functional phenotype, produce immunosuppressive cytokines (IL-10, IL-4, IL-13, and TGF-β) and angiogenesis factors, inhibit the antitumor response, cause T-cell dysfunction, and promote the growth and proliferation of tumor cells." (PMID 39858099, 2025). "Indeed, miR-146a is often induced by the IL-10-rich tumor environment and could enforce a “brake” on DC activation, supporting a state of immune equilibrium where T cells receive suboptimal stimulation." (PMID 40647470, 2025). "Thus, there is a need to consider how NK cells respond to IL-15 and how tumor-localized production of IL-15 (or IL-2, IL-21, or IL-10) is affected by therapeutics and how this therapy can be customized to address the likely insufficient cytokine receptor agonism within the TME." (PMID 40410571, 2025).
tumor (continued). "However, tumors develop sophisticated mechanisms to evade NK cell-mediated surveillance, ranging from ligand modulation (e.g., MIC-A/B shedding) to creating an immunosuppressive microenvironment dominated by TGF-β and IL-10, thus contributing to immune escape and tumor progression." (PMID 40299429, 2025). "However, the change in TNF-α and IL-10 may mean potentially complex mechanisms of action and changes in the tumor immune microenvironment." (PMID 40575154, 2025). "IL-10 may also predict therapy resistance: patients with high IL-10 can have dampened responses to immunotherapy or even chemotherapy, since an immunosuppressive microenvironment can protect tumor cells from cytotoxic immune-mediated death." (PMID 41007766, 2025). "CCL1 secretion is critical to maintain the M2b phenotype in mice and humans, while IL-10 has been found to impair the differentiation of infiltrated monocytes into mature dendritic cells (DCs), thereby compromising the competent host anti-tumor immune response." (PMID 39758935, 2025). "Conversely, IL-10 could also negatively regulate pro-inflammatory cytokines like IL-6 and IL-12/IL-23, maintain the homeostasis of anti-inflammatory Tregs, and suppress pro-inflammatory Th17 cells, which contribute to tumor growth." (PMID 39860614, 2025). "Moreover, IL-4 is thought to inhibit γδT cell-driven anti-tumor responses by directing the γδT cell population towards producing the immunosuppressive cytokine IL-10, thereby enhancing the expansion of the Vδ1+ subset and suppressing the IFN-γ-producing Vδ2+ subset." (PMID 40141420, 2025). "In BC, elevated levels of soluble PD‐L1 (sPD‐L1) enhance Breg proliferation and IL‐10 secretion, facilitating Treg differentiation and potentially leading to the exhaustion of Teff function, indicating that targeting Bregs may enhance anti‐tumor immunity." (PMID 40356222, 2025). "However, elevated IL-10 levels in the serum of BC patients may facilitate tumor immune evasion, as well as tumor growth and proliferation within the TME." (PMID 41153842, 2025). "Interestingly, IL-10 production delayed viral clearance from tumor tissues." (PMID 40350204, 2025). "HPV oncoproteins also modulate the tumor microenvironment, evading immune detection by altering major histocompatibility complex class I antigen expression and secreting immunosuppressive cytokines, such as IL-10, which hinder dendritic cell maturation and T-cell activation." (PMID 41261576, 2025). "DCs demonstrate functional duality: They orchestrate antitumor responses through tumor antigen presentation while concurrently suppressing cytotoxic T cell recruitment and down-regulating costimulatory molecule expression, thereby promoting immunosuppression via IL-10 and TGF-β secretion." (PMID 40948940, 2025). "Therefore, the therapeutic use of anti-IL-10 antibodies requires further investigation and may be highly context-dependent, varying with tumor type." (PMID 41011273, 2025). "Notably, IL10 may also have a direct effect on ALK-positive ALCL tumor cells because the ALCL cell line, SU-DHL1, expresses IL10 receptor subunits A and B in an ALK-dependent fashion." (PMID 41469691, 2025). "Within the TME, myeloid-derived suppressor cells (MDSCs), TAMs, tumor-associated neutrophils (TANs), Tregs, Bregs, and mature regulatory dendritic cells (mregDCs), collectively suppress cytotoxic lymphocytes through PD-1/PD-L1 and CTLA-4 engagement and by secreting IL-10, TGF-β, and VEGF." (PMID 41614820, 2025). "IL-10 and Abs may play key roles in tumor immunity mediated by TIL-B." (PMID 40688079, 2025). "Higher T-helper type 2 (Th2) cytokines (IL-4 and IL-10) in HCC are linked to HCC metastasis and progression, likely due to IL-4-initiated recruitment of TAM, leading to vascular endothelial growth factor (VEGF) and TGF-β secretion, contributing to tumor aggressiveness and metastasis." (PMID 40869156, 2025).
tumor (continued). "IL-10 and TGFβ are anti-inflammatory cytokines that, on the one hand, control the severity of autoimmune and inflammatory reactions and, on the other hand, play a negative role by damaging the host’s anti-tumor effector immunity and creating a favorable environment for tumor growth and metastasis." (PMID 40722593, 2025). "In HCC tumors, tumor-associated macrophages (TAMs) predominantly exhibit an M2-like phenotype, secreting vascular endothelial growth factor (VEGF), transforming growth factor-beta (TGF-β), and interleukin-10 (IL-10) to suppress cytotoxic T-cell activity and to facilitate pathologic angiogenesis." (PMID 40507341, 2025). "Additionally, IL-10 is secreted by tumor cells, further emphasizing its broad cellular origin." (PMID 40149345, 2025). "Combined blockade of IL-6 or IL-10 or IL-17 may better improve the prognosis of tumor patients." (PMID 40040705, 2025). "Monocytes, either directly or through differentiation into dendritic cells or tumor‐associated macrophages (TAMs), contribute to tumor growth by enhancing VEGF production, releasing IL‐6 and IL‐1, and suppressing cytotoxic T cell responses via IL‐10 and transforming growth factor‐beta (TGF‐β)." (PMID 41307215, 2025). "Interleukin-10 (IL-10) is another anti-inflammatory cytokine that suppresses the production of pro-inflammatory factors and inhibits the cytotoxic and cytokine-releasing functions of T cells, NK cells, macrophages, and dendritic cells, thereby diminishing anti-tumor immune responses." (PMID 39930476, 2025). "Despite these contrasting effects, sustained IL-10 signaling has emerged as a promising strategy for cancer immunotherapy, as it effectively activates and expands tumor-specific cytotoxic CD8+ T cells while concurrently mitigating tumor-associated inflammation." (PMID 40149345, 2025). "Natural killer (NK) cells induce cytotoxicity in tumor cells by releasing perforin and granzyme, while M2-type tumor-associated macrophages (TAMs) influenced by cytokines such as transforming growth factor-beta (TGF-β) and interleukin-10 (IL-10), and interact with tumor cells to promote i." (PMID 40242775, 2025). "In our study, GPC2-CAR T cell-treated mice tolerated treatment and had elevated levels of immune-suppressive interleukin-10 in their serum after tumor clearance, though these observations in xenograft mouse models may not accurately predict on-target off-tumor toxicities in the clinic." (PMID 41159102, 2025). "Additionally, tumor-secreted cytokines like IL-10 and TGF-β may inhibit typical macrophage activation and differentiation." (PMID 41374320, 2025). "They exposed human neutrophils to either a TAN1 cocktail (containing LPS, IFN-β, and IFN-γ) or a TAN2 cocktail (containing L-lactate, adenosine, TGF-β, IL-10, PGE2, and G-CSF) and demonstrated that each respective cocktail could polarize mature neutrophils into tumor-associated subsets." (PMID 40909277, 2025). "Additionally, IL-10 may inhibit invasion and migration capabilities of tumor by modulating extracellular matrix components within tumor microenvironment." (PMID 40535567, 2025). "IL-10 may be produced by either tumor cells themselves or by immune cells." (PMID 39202777, 2024). "However, TLS is also affected by tumor-produced cytokines and metabolic factors, such as TLS-associated Tregs, regulatory B cells (Bregs), interleukin-10 (IL-10), and enhanced antibodies, which lead to the formation of immunosuppressive TLS and macrophage or NK-cell-dependent apoptosis." (PMID 38816871, 2024). "However, as the tumour progresses, the number of M2b cells increases and gradually replaces the M1 cell population and promotes tumour progression by secreting factors such as IL-10, IL-6 and IL-1." (PMID 39060648, 2024). "Additionally, tumor cells could develop immune escape mechanisms including producing immunosuppressive cytokines (i.e., IL-10 or TGF-β) or presenting immunosuppressive receptors such as PD-L1." (PMID 39108768, 2024).